OR5M11 (olfactory receptor family 5 subfamily M member 11)
Description:
Odorant receptor.
Synonyms: OR11-199
Tractability: Antibody: UniProt places it where antibodies can reach, with medium confidence; UniProt predicts a signal peptide or a membrane-spanning region; its Gene Ontology location is reachable by antibodies, with medium confidence.
Gene: Protein-coding gene on chromosome 11 (56,542,340 to 56,543,257, reverse strand). Ensembl gene ENSG00000255223.
Subcellular location: Cell membrane
Pathways (Reactome):
Sensory Perception: Expression and translocation of olfactory receptors
Gene Ontology:
Molecular function: olfactory receptor activity; G protein-coupled receptor activity
Biological process: G protein-coupled receptor signaling pathway; sensory perception of smell; detection of chemical stimulus involved in sensory perception of smell
Cellular component: plasma membrane; membrane
Genetic constraint (gnomAD): Loss-of-function variants: 0 observed, 1.43 expected, observed/expected ratio (o/e) 0, 90% interval 0 to 1.58. That is too few expected variants to judge how well the gene tolerates losing a copy. Missense variants: 406 observed, 389.39 expected, observed/expected ratio (o/e) 1.04, 90% interval 0.96 to 1.13. Synonymous variants: 178 observed, 152.02 expected, observed/expected ratio (o/e) 1.17, 90% interval 1.04 to 1.33.
Homologues: Orthologues: chimpanzee OR5M11 (98% identical), dog OR5M11 (90% identical), rabbit OR5M11 (90% identical), mouse Or5m11 (86% identical), mouse Or5m11b (86% identical), rat Or5m11 (86% identical), rat Or5m11 (83% identical). Paralogues in human: OR5M10 (67% identical), OR5M1 (67% identical), OR5M8 (59% identical), OR5M3 (57% identical), OR8U3 (56% identical), OR5M9 (55% identical), OR8U1 (54% identical), OR8I2 (53% identical), OR8J1 (53% identical), OR5AP2 (53% identical), OR5F1 (52% identical), OR8B3 (52% identical), and 84 more.
Diseases named in the same sentence as OR5M11 in open-access papers:
OR5M11 is named in the same sentence as 4 diseases in open-access papers, as found by Europe PMC text mining. Sharing a sentence is not in itself a finding about the gene and the disease. The quoted sentences say what the papers report.
bacterial infection (1 paper, 2016). "Additionally, TAA has not been reported to interact with the G protein-coupled receptor OR5M11 yet; this research enriched the funcetion of OR5M11, and linked OR5M11 with the bacterial infection." (PMID 27046446, 2016).
infection (1 paper, 2016). The state of being infected such as from the introduction of a foreign agent such as serum, vaccine, antigenic substance or organism.
OR5M11 also shares sentences with these, for which no sentence is quoted: cancer (1 paper); lung adenocarcinoma (1).